DLK1 (delta like non-canonical Notch ligand 1)
Diseases named in the same sentence as DLK1 in open-access papers (continued):
Sharing a sentence is not in itself a finding about the gene and the disease.
intrauterine growth restriction (5 papers, 2013 to 2023). "Plagl1 was previously shown to regulate expression of Cdkn1c, Igf2, H19, and Dlk1 and to belong to a subset of IGs that control embryonic growth and differentiation, and loss of Plagl1 function resulted in intrauterine growth restriction." (PMID 36437415, 2023). "Imprinted genes such as DLK1 and NNAT are associated with gestational complications like preeclampsia and intrauterine growth restriction (IUGR), which can cost 3 times more than a normal birth in pre- to postnatal care 15-19." (PMID 37416777, 2023). "The reduction in weight of Dlk1-null embryos at E18.5 compared to their wild-type littermates suggests a role for Dlk1 in intrauterine growth retardation (IUGR)." (PMID 23279263, 2013). "Hypomethylation of the DLK1/MEG3 region results in Temple syndrome characterized by fetal growth restriction and shares many of the features of Silver Russell syndrome, including the downregulation of IGF2 expression, another paternally expressed imprinted gene." (PMID 33640968, 2021). "Because Dlk1 mutant neonates have a reduced weight at birth and Dlk1 has previously been shown to be expressed in the embryonic vessels of the placenta, we examined the placentas of Dlk1 mutant mice for any obvious aetiologies for intrauterine growth restriction." (PMID 23279263, 2013).
liver fibrosis (5 papers, 2008 to 2022). "This attenuation in liver fibrosis was also associated with an almost 50% reduction in Dlk1 mRNA expression." (PMID 35050550, 2022). "Advanced progression of liver fibrosis was associated with a parallel increase in circulating levels of DLK1, showing a significant increase in rats with cirrhosis (53.13 ± 5.66 ng/ml, P < 0.001)." (PMID 35050550, 2022). "Of note, we found that at MH stage, loss of FOXA2 led to a significant increase in the expression of mRNA levels of genes associated with hepatic fibrosis and HSC activation, such as PDGF, MMP2, TGFβ2, TGFβ3, TGFβR2, and DLK1 among others." (PMID 35973994, 2022). "Overall, our findings indicate that the PTTG1/DLK1 pathway is relevant in the pathogenesis of liver fibrosis." (PMID 35050550, 2022). "While little is known about its involvement in liver fibrosis, PTTG1 expression is associated with DLK1." (PMID 35050550, 2022). "This was the first publication suggesting correlation between DLK1 expression and soluble DLK1 concentration in liver fibrosis." (PMID 35805898, 2022). "PTTG1/DLK1 signalling is a novel pathway for targeting the progression of liver fibrosis." (PMID 35050550, 2022). "In summary, these findings further support the hypothesis that PTTG1/DLK1 signaling could be a novel pathway for targeting the progression of liver fibrosis." (PMID 35805898, 2022). "Interestingly, MMP9-immunopositive cells, irrespective of their origin from ES cells or the recipient, were immunopositive for DlK-1, a hepatoblast marker, suggesting that hepatoblast-like cells play an important role in the regression of liver fibrosis." (PMID 19134049, 2008). "Thus, the PTTG1/DLK1 axis may represent a valuable target for the prevention and treatment of liver fibrosis." (PMID 35050550, 2022). "On the other hand, DLK1 has been identified as one of the most abundantly expressed PTTG1 targets in adipose tissue and has shown to contribute to hepatic fibrosis by promoting the activation of hepatic stellate cells." (PMID 35805898, 2022). "Based on the concept that DLK1 is one of the most abundantly expressed PTTG1 targets, we recently documented the close link between DLK1 and PTTG1 in the progression of liver fibrosis." (PMID 35805898, 2022).
lupus (5 papers, 2016 to 2024). "In the current study, we found that Egr2 deletion in B6/lpr mice significantly reduced the expression of DNA methylation–sensitive Dlk1-Dio3 miRNAs, which are upregulated and implicated in the pathogenesis of autoimmune diseases such as lupus and MS." (PMID 38153351, 2023). "This study aims to understand the molecular mechanism underlying the DNA hypomethylation and the upregulation of Dlk1-Dio3 miRNAs in lupus CD4+ T cells." (PMID 38153351, 2023). "We reported here that deliberate inhibition of selected DLK1-Dio3 miRNAs such as miR-154, miR-379, and miR-300 significantly reduced the production of lupus-associated cytokines IFNγ, IL-1β, IL-6, and/or IL-10." (PMID 27070142, 2016). "In a previous purely computational prediction analysis, DLK1-Dio3 miRNAs were predicted to target numerous lupus susceptibility genes." (PMID 27070142, 2016). "However, the molecular mechanism underlying the DNA hypomethylation and the upregulation of Dlk1-Dio3 miRNAs in lupus CD4+ T cells remains unclear." (PMID 38153351, 2023). "We previously demonstrated that the upregulation of microRNAs (miRNAs) at the genomic imprinted Dlk1-Dio3 locus in murine lupus is correlated with global DNA hypomethylation." (PMID 38153351, 2023). "Although the role of methylation in EGR2-mediated regulation of Dlk1-Dio3 miRNAs is not readily apparent, these are the first data to show that in lupus, Egr2 regulates Dlk1-Dio3 miRNAs, which target major signaling pathways in autoimmunity." (PMID 38153351, 2023). "Of these dysregulated miRNAs in lupus, a group of miRNAs is located at the genomic imprinted delta-like homolog 1–type 3 iodothyronine deiodinase (Dlk1-Dio3) locus, which possesses the largest miRNA cluster in human and murine genome." (PMID 38153351, 2023). "The dysregulation of miRNAs located at the genomic imprinting Dlk1-Dio3 locus has been identified in various types of cancers and autoimmune diseases, including MS and lupus." (PMID 38153351, 2023). "It is possible that EGR2 regulates autoimmunity in lupus mice via the regulation of Dlk1-Dio3 miRNAs." (PMID 38153351, 2023). "In this study, we reported that Egr2 deletion significantly reduced maternally expressed Dlk1-Dio3 miRNAs, suggesting that EGR2 plays an important role in the upregulation of Dlk1-Dio3 miRNAs in murine lupus CD4+ T cells." (PMID 38153351, 2023). "The dysregulation of Dlk1-Dio3 miRNAs has also been identified in both human and murine lupus studies." (PMID 34062726, 2021). "They discovered nine signature lupus-related miRNAs, of which two (miR-134 and miR-409) are from the Dlk1-Dio3 locus." (PMID 34062726, 2021). "Although the target gene/pathways remains to be experimentally determined, we demonstrated here that inhibition of specific DLK1-miRNAs with antagomirs reduced the production of lupus-relevant cytokines in LPS-activated splenocytes from MRL-lpr mice." (PMID 27070142, 2016). "The dysregulated expression of selected DLK1-Dio3 miRNAs such as miR-134, miR-433, miR-494, and miR-379 has also been noticed in human lupus." (PMID 27070142, 2016). "This indicates a potential role of genomic imprinted DLK1-Dio3 miRNAs in regulation of inflammation in lupus." (PMID 27070142, 2016). "It is necessary to investigate the potential involvement of histone modification alteration in the LOI and dysregulation of DLK1-Dio3 miRNAs in lupus in future study." (PMID 27070142, 2016). "Our study is the first to show that DNA methylation regulates genomic imprinted DLK1-Dio3 miRNAs in autoimmune lupus, which suggests a connection of DNA methylation, miRNA and genomic imprinting in lupus pathogenesis." (PMID 27070142, 2016). "Nevertheless, there is thus far limited understanding of the regulation and immune regulatory function of DLK1-Dio3 miRNAs in lupus." (PMID 27070142, 2016).
lupus (continued). "The Kyoto Encyclopedia of Genes and Genomes pathway enrichment analysis of the predicted target genes of the Dlk1-Dio3 miRNAs that are upregulated in murine lupus or in MS showed the enrichment of signaling cascades that have been implicated in autoimmune disease pathogenesis." (PMID 38153351, 2023). "Another Dlk1-Dio3 miRNA that was reported to be reduced in the human lupus PBMCs is miR-379." (PMID 34062726, 2021). "In addition to the lpr lupus model, the upregulation of selected Dlk1-Dio3 miRNAs has also been observed in the splenocytes of the other murine lupus murine models, NZBWF1 mice and C3.MRL-Faslpr/J mice (miR-127 and miR-379)." (PMID 34062726, 2021). "Our previous miRNA microarray profiling study identified that selected miRNAs from the Dlk1-Dio3 locus were significantly upregulated in lupus cells, which included miR-127, miR-154, miR-299, miR-300, miR-329, miR-376b, miR-379, miR-382, miR-411, miR-433, and miR-494." (PMID 34062726, 2021). "Strikingly, across three genetic mouse models of systemic lupus erythematosus, in which the inflammatory autoimmune reaction is characterized by aberrant autoantibody production, numerous Dlk1-Dio3 locus miRNAs were progressively upregulated in splenic T and B lymphocytes during lupus development." (PMID 30190790, 2018). "Further, different mechanism other than LOI may be also involved in the upregulation of DLK1-Dio3 miRNAs in lupus." (PMID 27070142, 2016). "While the current study focused on the DNA methylation regulation of genomic imprinted DLK1-Dio3 miRNAs in lupus, it is noteworthy that DNA methylation may interact with histone acetylation to regulate the imprinting of DLK1-Dio3 locus." (PMID 27070142, 2016). "Together, our data indicated that DLK1-Dio3 miRNAs might play a role in the regulation of different lupus-related cytokines." (PMID 27070142, 2016). "Finally, inhibition of select DLK1-Dio3 miRNA such as miR-154, miR-379 and miR-300 with specific antagomirs significantly reduced the production of lupus-relevant IFNγ, IL-1β, IL-6, and IL-10 in lipopolysaccharide (LPS) activated splenocytes from MRL-lpr mice." (PMID 27070142, 2016). "Moreover, we demonstrated that DLK1-Dio3 miRNAs play a role in regulation of inflammation in lupus by regulating the production of lupus-related cytokines." (PMID 27070142, 2016). "Conceivably, upregulated DLK1-Dio3 miRNAs such as miR-154, miR-379, and miR-300 might accelerate lupus by promoting the production of lupus-related cytokines." (PMID 27070142, 2016). "In this study, we reported that a large cluster of miRNAs from the genomic imprinted DLK1-Dio3 domain is significantly upregulated in splenic cells from MRL-lpr lupus mice when compared to control MRL mice, and that this upregulation is associated with DNA hypomethylation in lupus cells." (PMID 27070142, 2016). "To test the potential epigenetic regulatory role of EGR2 in lupus CD4+ T cells, we evaluated the expression of selected methylation-sensitive Dlk1-Dio3 miRNAs, which are highly upregulated in lupus (e.g., miR-127, miR-154, miR-300, miR-279, and miR-433)." (PMID 38153351, 2023). "Further, we found that in vitro inhibition of specific Dlk1-Dio3 miRNAs such as miR-154, miR-379, and miR-300 in MRL-lpr splenocytes suppressed the production of LPS-induced, lupus-related cytokines such as IFNγ, IL-1β, IL-6, and IL-10." (PMID 34062726, 2021). "The dysregulation of DLK1-Dio3 miRNAs was also evident in B6-lpr and NZB/WF1 lupus mice (such as miR-127 and miR-379), and in human lupus patients (such as miR-134, miR-379, and miR-433)." (PMID 27070142, 2016). "This implies a potential important contribution of DLK1-Dio3 miRNAs to both murine and human lupus, an aspect not known yet." (PMID 27070142, 2016).
lupus (continued). "In our previous study of profiling dysregulated miRNAs in different murine lupus models with miRNA microarray, we found that 11 out of the 17 upregulated miRNAs in splenocytes of MRL-lpr mice belong to the largest miRNA cluster located at the genomic imprinted DLK1-Dio3 region." (PMID 27070142, 2016).
melanoma (5 papers, 2016 to 2025). A malignant, usually aggressive tumor composed of atypical, neoplastic melanocytes. "Moreover, DLK1 has been suggested to be positively associated with cell growth in melanoma cells." (PMID 32051829, 2020). "miR-127 blocked the development of melanoma by targeting DLK1, providing a novel biomarker for the treatment of melanoma." (PMID 32051829, 2020). "In this study, we first validated the association of miR-127 and DLK1 and indicated that restoration of DLK1 reversed the regulatory effect of miR-127 on cell proliferation and apoptosis in melanoma cells." (PMID 32051829, 2020). "Results showed that a great increase of DLK1 mRNA level was indicated in melanoma tissues compared with that in adjacent samples." (PMID 32051829, 2020). "In the present study, we measured the expressions of miR-127 and DLK1 in melanoma tissues and cells and explored the potential mechanism that underlies miR-127 regulating progression of melanoma in vitro and in vivo." (PMID 32051829, 2020). "In the present study, we investigated the role of miR-127 in the progression of melanoma and provided the first integrative view that miR-127 inhibited cell proliferation and induced apoptosis in melanoma cells by targeting DLK1." (PMID 32051829, 2020). "The expressions of miR-127 and delta-like homologue 1 (DLK1) were measured in melanoma tissues and cells by quantitative real-time polymerase chain reaction (qRT-PCR) and Western blot." (PMID 32051829, 2020). "Seeing that DLK1 was targeted by miR-127, the expression of DLK1 was detected in melanoma tissues and cells." (PMID 32051829, 2020). "The epigenetic silencing of the imprinted DLK1-Dio3 miRNA cluster has been documented in melanoma, ovarian, and bladder cancer, and many DLK1-Dio3 miRNAs have tumor suppressor function." (PMID 27070142, 2016). "Furthermore, DLK1 was directly targeted by miR-127 and its overexpression abated the effect of miR-127 on the progression of melanoma." (PMID 32051829, 2020). "Moreover, DLK1 was targeted by miR-127 and its restoration reversed the regulatory effect of miR-127 on the process of melanoma." (PMID 32051829, 2020). "miR-127 was inhibited and DLK1 mRNA was enhanced in melanoma tissues and cells." (PMID 32051829, 2020). "Hence, we established melanoma cells xenograft model in vivo and suggested that miR-127 suppressed tumor growth by regulating DLK1 in mice." (PMID 32051829, 2020). "In summary, miR-127 was downregulated and DLK1 was upregulated in melanoma tissues and cells." (PMID 32051829, 2020). "Moreover, the DLK1 mRNA level was negatively correlated with miR-127 abundance in melanoma patients (r2 = 0.2479, p=0.0011)." (PMID 32051829, 2020). "Besides, it has been indicated that DLK1 facilitates cell proliferation and oncogenic potential of melanoma cells." (PMID 32051829, 2020). "Similarly, the mRNA expression of DLK1 was also increased in melanoma cells compared with that in HeMa-Lp cells." (PMID 32051829, 2020). "Hence, we speculate that DLK1 may be required for miR-127-mediated effect on the progression of melanoma." (PMID 32051829, 2020). "It was reported that, similarly to DLK1, DLK2 affects the growth of SK-MEL-2 melanoma cells, and the nature of its effects depends upon DLK2 expression levels and the degree of inhibition of NOTCH1 activation." (PMID 35163478, 2022).
muscular dystrophy (5 papers, 2019 to 2025). Muscular dystrophy (MD) refers to a group of more than 30 genetic diseases characterized by progressive weakness and degeneration of the skeletal muscles that control movement. "In the context of muscular dystrophy, we recently demonstrated the participation of the Dlk1-Dio3 miR-379 in the modulation of mitochondrial activity in the dystrophic muscle." (PMID 36265896, 2023). "Here we demonstrate that in DMD and other muscular dystrophies, a large number of Dlk1-Dio3 clustered miRNAs (DD-miRNAs) are coordinately up-regulated in regenerating myofibers and in the serum." (PMID 36265896, 2023). "Importantly, accompanying the progression of the disease, the accumulation of adipocytes is increased in DMD patients, and Dlk1 is re-expressed in skeletal muscle of DMD and other muscular dystrophy patients, suggesting that Dlk1 expression level might be correlated with fat accumulation." (PMID 31277245, 2019).
autoimmune disease (4 papers, 2013 to 2023). A disorder resulting from loss of function or tissue destruction of an organ or multiple organs, arising from humoral or cellular immune responses of the individual to their own tissue constituents. "Dlk1-Dio3 miRNAs have been recently implicated in the pathogenesis of autoimmune disease MS and EAE." (PMID 34062726, 2021). "Further, we specifically discuss the genetic imprinting Dlk1-Dio3 miRNAs that are subjected to DNA methylation regulation and are dysregulated in several autoimmune diseases, including SLE." (PMID 34062726, 2021). "Our study highlights for the first time Dlk1 as a regulator of the adaptive immune responses and an autoimmune disease that models MS." (PMID 24676147, 2014). "Further investigation is warranted to understand the contribution of Dlk1-Gtl2 (or human DLK1-DIO3) genomic imprinted miRNAs to autoimmune disorders." (PMID 24175965, 2013). "Recent studies revealed that Dlk1-Dio3 miRNAs are dysregulated in autoimmune disease and that the Dlk1-Dio3 locus may play a role in the parent-of-origin effect of autoimmune disease." (PMID 34062726, 2021). "Further, we specifically discuss the dysregulation of genetic imprinting Dlk1-Dio3 miRNAs in autoimmune disease, which may provide us with a new perspective for understanding the epigenetic mechanism and the role of genomic imprinting in autoimmune disease." (PMID 34062726, 2021).
Hepatic steatosis (4 papers, 2019 to 2022). Steatosis is a term used to denote lipid accumulation within hepatocytes. "Furthermore, gene structural analysis has revealed that, by directly targeting DLK1, different miRNA represses its expression, resulting in hepatic steatosis." (PMID 35805898, 2022). "Interestingly, the exogenous administration of DLK1 in mice reduced hepatic steatosis and hyperglycemia via AMPK activation in the liver." (PMID 31460623, 2019). "It has been proposed that DLK1 may alter the metabolic mode of the organism from lipid storage to peripheral lipid oxidation, protecting the organism from hepatic steatosis." (PMID 31460623, 2019).
liver cancer (4 papers, 2013 to 2024). An epithelial or non-epithelial malignant neoplasm that arises from the liver. "DLK1, which encodes a transmembrane protein and is involved in cell differentiation, has been linked to liver cancer development and progression." (PMID 23890537, 2013). "We next evaluated the binding of CBA-1205 to Hep3B and HepG2 cells, human liver cancer cell lines that express endogenous DLK1 on the cell surface." (PMID 39769389, 2024). "DLK1 knockdown in liver cancer cell lines was shown to suppress colony formation in vitro and tumor growth in vivo." (PMID 39769389, 2024). "Our results demonstrate the antitumor activity of CBA-1205 in the liver cancer models, suggesting a potential therapeutic strategy by depletion of DLK1-positive cancer stem cells in HCC by ADCC activity of CBA-1205." (PMID 39769389, 2024). "Previous studies showed that DLK1-expressing sub-populations in human liver cancer cell lines exhibit cancer stem cell–like properties, such as high proliferative capacity, high invasiveness, and resistance to chemotherapy." (PMID 39769389, 2024). "Suppression of endogenous DLK1 expression resulted in decreased cell growth, colony formation, and tumorigenicity in human-derived liver cancer cell lines." (PMID 35805898, 2022). "We demonstrated the long-lasting anti-tumor efficacy of the afucosylated humanized anti-DLK1 antibody CBA-1205 as a single agent and in combination treatment with lenvatinib in two liver cancer cell xenograft mouse models." (PMID 39769389, 2024). "A number of markers, including CD13, CD44, CD24, CD90, CD133, EpCAM, DLK1, ALDH1 can be used to identify liver cancer stem cells." (PMID 28930164, 2017). "In an experiment with 17 different liver cancer (mainly HCC) cell lines, the DLK1-positive sub-populations isolated from each cell line showed higher in vitro colony formation and cell proliferation activities and increased in vivo tumorigenic potential compared with DLK1-negative sub-populations." (PMID 39769389, 2024).